IL17A (interleukin 17A)
Diseases named in the same sentence as IL17A in open-access papers (continued):
Sharing a sentence is not in itself a finding about the gene and the disease.
Candidemia (7 papers, 2016 to 2025). A form of invasive candidiasis where species of CANDIDA are present in the blood. "The IL-17 family consists of IL-17A to IL-17F; the roles of IL-17A and IL-17C cytokines have been of great interest in the context of candidemia." (PMID 41229429, 2025). "Proinflammatory chemokines, INF-γ and IL-17A, were found to be significantly upregulated in both groups with candidemia compared to controls." (PMID 41229429, 2025). "Bacterial infection triggers both IL-17A and IL-17C, whereas candidemia exhibits a contradictory pattern, upregulating IL-17A and downregulating IL-17C." (PMID 41229429, 2025). "Chemokines and IL-17A upregulation in all candidemia cases align with current understanding of immunity against Candida." (PMID 41229429, 2025). "Other cytokine and chemokine biomarkers, including macrophage inflammatory protein-1β, interleukin 17A (IL-17A), and kynurenine, to name but a few, were also proposed for the detection of candidemia using Luminex xMAP technology, but their clinical usefulness remains controversial." (PMID 41237902, 2025). "Interestingly, IL-17A expression was notably increased, while IL-17C was significantly decreased in candidemia, indicating distinct functions for different IL-17 cytokine family members in this condition." (PMID 41229429, 2025). "The most interesting result of our investigation was the significantly higher levels of the pro-inflammatory Th17 type cytokine, IL17A and IL-6, in the serum samples from patients with candidemia in comparison with samples from patients with bacterial infections and the healthy subjects." (PMID 34684298, 2021). "Interleukin 17A (IL-17A), the major cytokine secreted by T helper type 17 cells, as well as kynurenine, showed time-dependent elevations in candidemic patients compared to non-candidemic patients with significantly higher values in the early course of candidemia compared to later stages." (PMID 33535593, 2021). "The significant correlation between IL-17A and L-KYN levels with candidemia suggests their potential as biomarkers, and understanding the interaction between the oral microbiome, oral diseases, and the KP could guide therapeutic strategies." (PMID 39590344, 2024). "A recent study found that patients with candidemia had significantly higher levels of IL-17A and L-KYN compared to those without candidemia." (PMID 39590344, 2024). "Serum IL-17A and IL-6 levels could not be detected in the healthy control group, whereas, in comparison with the bacterial group, the candidemia group had significantly elevated levels of these cytokines." (PMID 34684298, 2021).
chronic gastritis (7 papers, 2016 to 2025). Inflammation of the stomach that is chronic in nature. "Importantly, our results together identify a multi-step model of persistent H. pylori infection accompanied with chronic gastritis involving cross-talks between H. pylori, IL-17A, GECs, ANGPTL4, neutrophils, monocytes, as well as Tregs." (PMID 39022746, 2024). "Additionally, IL-17A depletion attenuated the degrees of chronic gastritis and preneoplastic lesions, clearly indicating an oncogenic role in GC development." (PMID 36125689, 2023). "Serum IL-17A concentration was statistically significant between healthy controls and patients with mild chronic gastritis (p = 0.0001) and with moderate to severe chronic gastritis (p = 0.0136)." (PMID 29391865, 2017). "Expression of serum cytokines (IL-17A, IL-21, IL-23, IL-10, and TNF-α) in H. pylori-infected patients was compared with healthy controls and correlated with disease severity (mild chronic gastritis, moderate chronic gastritis, and severe chronic gastritis)." (PMID 29391865, 2017).
chronic lymphocytic leukemia (7 papers, 2013 to 2021). "IL-17A may be beneficial in chronic lymphocytic leukemia development, since its levels are inversely correlated with the time between the disease diagnosis and start of the therapy, and its levels are lower in patients who require treatment during the follow-up20." (PMID 32341381, 2020).
colon adenocarcinoma (7 papers, 2013 to 2024). "We found that IL-17A levels were higher in colon adenocarcinoma tissue and almost undetectable in normal colon tissue." (PMID 37211606, 2023). "We observed that CCL20 and IL-17A expression in colon adenocarcinoma (COAD) and rectal adenocarcinoma (READ) tissues were higher than the expression in other cancer tissues." (PMID 31387598, 2019). "In addition, IL-17A or TNF- α cytokine induces IL-8 (a human homologue of KC) expression in human colon adenocarcinoma cells." (PMID 31540059, 2019). "Further Kaplan‒Meier analysis of colon adenocarcinoma(COAD) data in the GEPIA database indicated relatively high expression of IL-17A in CRC patients with better survival (p = 0.027 < 0.05)." (PMID 37211606, 2023).
cyst (7 papers, 2019 to 2026). A sac-like closed membranous structure that may be empty or contain fluid or amorphous material. "As the infection progresses, a permanent T1-type response follows (high levels of IFN-γ and IL-17A) by 8 weeks, which limits the growth of established cyst forms in the liver in the murine model." (PMID 36046744, 2022). "For cyst type CE3 in Year 3, levels of IL-17A, IL-8, IL-1β, MIP-1α and MIP-1β were slightly elevated relative to those in CE4 in Year 2 whereas IL-2, TNF-α, IL-1Rα and G-CSF maintained stable levels." (PMID 32171321, 2020).
demyelination (7 papers, 2013 to 2025). "In both the brains and spinal cord of IL-17A-/- mice that received T cells transfer and demonstrated demyelination, 60 genes were upregulated, while 43 genes were downregulated." (PMID 36817487, 2023). "Also in Cuprizone-induced demyelination we were able to demonstrate the early recruitment of neutrophils into the CNS by local IL-17A production." (PMID 36857006, 2023).
esophageal adenocarcinoma (7 papers, 2020 to 2023). A malignant tumor with glandular differentiation arising predominantly from Barrett mucosa in the lower third of the esophagus. "Moreover, IL-17A is reported to cause an increase in intracellular ROS in esophagus adenocarcinoma and vascular smooth muscle cells." (PMID 36125689, 2023). "Multiple studies have shown that cases with esophageal adenocarcinomas demonstrated lesser levels of IL-17A than healthy controls." (PMID 35480154, 2022). "In our previous study, we found a pro-invasion effect of IL-17A in esophageal adenocarcinoma cells." (PMID 32489459, 2020). "Exposure of Barrett’s and esophageal adenocarcinoma cells to acidic bile salts activated EGFR-Stat3 signaling (EGFR-STAT3 protein complex) and induced the expression of Stat3 target genes (IL-6, IL-17A, BCL-xL, Survivin, and c-MYC)." (PMID 34884765, 2021).
fibromyalgia (7 papers, 2018 to 2025). A chronic disorder of unknown etiology characterized by pain, stiffness, and tenderness in the muscles of neck, shoulders, back, hips, arms, and legs. "Plasma levels of IL-17A are elevated in patients with fibromyalgia and in mice, IL-17 contributes to neuroinflammatory responses and pain hypersensitivity following neuropathic injury." (PMID 29880010, 2018). "In addition, fibromyalgia patients displayed lower concentrations of IFN-γ, IL-12, and IL-17A compared with the healthy controls, consistent with immunoreactions induced via TLR4 signaling." (PMID 41007675, 2025).
gestational diabetes (7 papers, 2016 to 2025). Carbohydrate intolerance first diagnosed during pregnancy. "Here we examined umbilical cord IL-17A levels and their link to gestational diabetes mellitus (GDM) and perinatal infections (PIs)." (PMID 40894398, 2025).
Headache (7 papers, 2017 to 2025). Cephalgia, or pain sensed in various parts of the head, not confined to the area of distribution of any nerve. "When the ROC curve was drawn with headache as the state variable, the results showed that IL-17A alone had the optimal prediction effect, but the observational data did not fit well with the regression model." (PMID 38356891, 2024). "Regarding the central tendency measures, in the comparison of the crude median values of cytokines, we observed that patients with headache had higher median values of GROa, IFN-gamma, IL-10, IL-13, IL-15, IL-17a, IL-21, IL-22, IL-27 and IL-6." (PMID 34088273, 2021). "Zika virus-infected subjects who reported headaches showed higher plasma levels of TNF-α, IL-17A, IL-2, IL-9, IL-12p70, MIP-1α, G-CSF, GM-CSF, and VEGF, and significantly higher levels of IL-5 (p = 0.0015) compared to those without headache." (PMID 29774022, 2018).
hookworm infection (7 papers, 2011 to 2023). "Levels of the Th17-associated genes, IL-17A and RORγt, were both extremely low, close to or below the detection limit of the assay, but nevertheless appeared unchanged after hookworm infection." (PMID 22346753, 2012). "In TB patients, on the other hand, only hookworm infection showed a similar pattern suppressing Th1 cytokines in PBMC, as well as suppressing the elevated systemic levels of IL-17A in plasma." (PMID 35976976, 2022). "Moreover, we demonstrated that the IL-17A response by SEB stimulated PBMCs was higher in S. mansoni infected CCs, whilst hookworm infection in TB patients instead significantly reduced plasma IL-17A." (PMID 35976976, 2022). "Levels of QE65-specific IL-2, IFN-γ or IL-17A did not appear to change after hookworm infection or challenge." (PMID 21949691, 2011). "However, we did not observe any evidence that hookworm infection supressed systemic pro-inflammatory cytokine levels other than modest and transient reductions in IL-17A." (PMID 37495576, 2023). "Hookworm infection suppressed basal production of the inflammatory cytokines IFN-γ and IL-17A, and our data indicate that this suppression may be dependent upon skewing or cross-regulation of the celiac response by a concurrent TH2 response, and/or IL-10 production." (PMID 21949691, 2011).
Hyperinsulinemia (7 papers, 2016 to 2023). An increased concentration of insulin in the blood. "We aimed to determine the risk association of hyperinsulinemia in NMOSD patients with seropositive AQP4-IgG and the serum levels of interleukin (IL)-6 and IL-17A compared with the control group." (PMID 33879088, 2021). "In the hyperinsulinemia/euglycemic clamp model of EL, the cohort of genes examined included few downstream targets of IL-17A activation, but these studies identified both MMP9 and TNFα upregulation." (PMID 33301461, 2020).
nematode infection (7 papers, 2015 to 2025). "Circulating IL-17A levels were determined throughout the trials like IL-17 involved in the establishment of tissue repair during parasitic nematode infections." (PMID 33407892, 2021). "Our original hypothesis was that in the presence of IL-17A, macrophage-neutrophil cocultures will display improved bacteria killing, but the trade-off would be increased release of enzymes that cause tissue damage, such as neutrophil elastase in a model of nematode infection." (PMID 30455194, 2019).
osteonecrosis (7 papers, 2017 to 2024). A none disease characterized by death of bone tissue due to a lack of blood supply. "Interestingly, osteonecrosis induced by infectious osteomyelitis plus alendronate administration was significantly blocked in either IL-1α/β (IL-1 KO)- or IL-6-deficient (IL-6 KO) mice, and was weakly attenuated in IL-17A/F-deficient (IL-17 KO) mice." (PMID 28387378, 2017). "In recent studies, pro-inflammatory cytokines, interleukin 33 (IL33), and interleukin 17A (IL17A), which are members of the interleukin 1 (IL1) family, play roles in osteonecrosis." (PMID 34305456, 2021). "It has been shown that increased serum levels of IL-17A and IFN-γ are present in patients with steroid-related osteonecrosis." (PMID 33132753, 2020).
polyposis (7 papers, 2015 to 2025). "We previously showed that ablation of IL-17A in Apc/Min+ mice achieved approximately 90% inhibition of polyposis even at 20 weeks, suggesting that the effect of IL-17A deficiency is long-lasting to inhibit the formation of a tumor microenvironment." (PMID 26146642, 2015). "Specifically, IL-1 and IL-17a hyperactivate the mucin production by goblet cells through nuclear factor κB signaling, and abnormal mucin accumulation results in the morphological changes, epithelial barrier destruction, and polyposis development." (PMID 37889976, 2023).
thrombosis (7 papers, 2017 to 2025). "In addition, a recent study reports that IL-17A promotes deep vein thrombosis in humans and mice by enhancing platelet activation/aggregation, neutrophil infiltration, and endothelial cell activation." (PMID 33353549, 2020). "In addition, given the possible role played by IL17 in the pathogenesis of massive intravascular thrombosis, the use of an anti-IL-17A neutralizing monoclonal antibody should be also proposed as a potential strategy." (PMID 33353549, 2020).
trachoma (7 papers, 2013 to 2024). "The authors concluded that IL-17A and Th17 responses play a central pro-inflammatory role in trachoma." (PMID 39093884, 2024). "The importance of EMT in trachomatous scarring has been contemplated based on the finding that active trachoma is associated with increased expression of profibrotic cytokines, such as CTGF and IL-17A, which are known for their capability to induce EMT." (PMID 28660176, 2017). "MMP7, CXCL5 and IL-17A were strongly associated with inflammatory episodes but not with progressive scarring in two large cohorts of individuals with trachoma." (PMID 27249027, 2016). "IL-17A, CXCL5, PDGF, MMP7 and MMP9 have previously been associated with various stages of trachoma (trachomatous inflammation–follicular, TS and TT) at mRNA and protein expression levels, however they were not demonstrably up-regulated in TT cases in the present study." (PMID 27249027, 2016). "Initial studies suggest that IL-17A may be important in trachoma pathogenesis." (PMID 23457650, 2013). "This is interesting and possibly indicates that IL-17A expression in koalas, may not be the main contributor to inflammation at the conjunctival site, despite reports of active trachoma in children being associated with increased expression of IL-17A at the conjunctival site." (PMID 30615687, 2019).
acute pancreatitis (6 papers, 2021 to 2025). An acute inflammatory process that leads to necrosis of the pancreatic parenchyma. "qPCR data also confirmed the upregulated levels of IL‐23a, IL‐17a, and IL‐17f and the downregulated levels of ATM, Cdk2, and Chk2 in the pancreatic tissues of mice with acute pancreatitis." (PMID 35634959, 2022). "RNA‐seq data discovered that compared to untreated mice, IL‐23a, IL‐17a, and IL‐17f were remarkably increased while cell cycle‐related molecules, including ATM, Cdk2, and Chk2, were decreased in the mice with acute pancreatitis." (PMID 35634959, 2022).
bacterial meningitis (6 papers, 2014 to 2024). Inflammation of the membranes surrounding the brain and spinal cord due to a bacterial infection. "Cytokines IL-2, IL-17A, and the chemokine MIP-3α (CCL20) have also been shown to be associated with bacterial meningitis and promote BBB disruption (46, –, 49)." (PMID 39400158, 2024).
carotid atherosclerosis (6 papers, 2017 to 2025). A thickening and loss of elasticity of the walls of carotid arteries that occur with formation of atherosclerotic plaques. "Studies have shown that IL-17A stimulation in human carotid atherosclerosis results in elevated expression of proinflammatory markers." (PMID 40089108, 2025). "Our findings indicate that CXCL16, IL-17A, and TGF-β levels can be correlated with each other, forming a positive feedback regulatory loop among the three factors and promoting the development of carotid atherosclerosis." (PMID 40165931, 2025). "Moreover, a positive feedback loop exists between CXCL16 and inflammatory factors such as IL-17A and TGF-β, mutually promoting their expression and accelerating carotid atherosclerosis progression via activation of the STAT3 and NF-κB pathways." (PMID 40165931, 2025).
cerebral malaria (6 papers, 2017 to 2024). A sequestration of Plasmodium falciparum in the brain, which can cause coma and/or seizures. "In addition to TNF, the cytokines IFN-γ and IL-17A have also been associated with an increased risk of developing cerebral malaria." (PMID 38256880, 2023). "We suggest that IL-22, acting in synergy with IL-17A, may have a deleterious effect in cerebral malaria, through the direct or indirect promotion of BBB permeability and brain inflammation, whilst protecting infected individuals against blood-stage infections and fatal liver tissue damage." (PMID 28139719, 2017).
cutaneous T-cell lymphoma (6 papers, 2016 to 2024). "In cutaneous T-cell lymphoma, GD3 inhibits the production of IL-17A as a mechanism of suppressive antitumor immunity." (PMID 35873547, 2022).
glomerulosclerosis (6 papers, 2019 to 2023). A hardening of the kidney glomerulus caused by scarring of the blood vessels. "In the pathological findings, glomerulosclerosis, interstitial infiltration, and macrophage infiltration were significantly attenuated in IL-17A vaccine-immunized MRL/lpr mice 18 weeks after vaccination." (PMID 32059488, 2020). "Similarly, other cytokines such as IL17A, interferon (IFN)-α, and IFN-β were found to be involved in glomerulosclerosis." (PMID 31906131, 2019).
gonorrhea (6 papers, 2018 to 2025). A common sexually transmitted bacterial infection caused by Neisseria gonorrhoeae. "As gonococcal infection drives a Th17 response, we examined the production of IL-17A as an indicator of Th17 responses." (PMID 39541395, 2024). "In a study from 2011, the serum concentrations of IL-17A, IL-23 and IFN-γ were analyzed in 27 patients (consisting of 16 men and 1 woman, recruited from Rome and Turin, Italy, with median age of 37.5 years) with gonorrhea and compared to 17 healthy controls." (PMID 37662926, 2023).
Graves ophthalmopathy (6 papers, 2017 to 2024). An autoimmune disorder of the EYE, occurring in patients with Graves disease. "On the other hand, IL-17A promoted ACTA2 expression in orbital fibroblasts in thyroid-associated ophthalmopathy." (PMID 32670268, 2020). "Moreover, we would like to study not only the role of IL-17A, but also its link to the inflammasome-related phenomenon occurring in the course of Graves’ orbitopathy." (PMID 37109536, 2023).
hyperhomocysteinemia (6 papers, 2020 to 2025). A serious metabolic condition caused by mutations in the MTHFR gene, medications, or nutritional deficiency. "NSun2 mediated hyperhomocysteinemia-induced upregulation of IL-17A expression by methylating IL-17A mRNA and promoting its translation in T lymphocytes." (PMID 41462962, 2025). "The m5C methyltransferase NSUN2 mediates the upregulation of interleukin-17a (IL-17A) induced by hyperhomocysteinemia by methylating IL-17A mRNA and enhancing its translation in T lymphocytes." (PMID 39726589, 2024). "NSUN2 methylates interleukin-17A (IL-17A) mRNA to mediate the hyperhomocysteinemia (HHcy)-induced upregulation of IL-17A expression and promotes its translation in T lymphocytes." (PMID 35562754, 2022). "Furthermore, Nsun2 methylates Il17a mRNA and promotes its mRNA translation in rat total T lymphocytes upon hyperhomocysteinemia treatment." (PMID 36792629, 2023). "In hyperhomocysteinemia, NSUN2 upregulates IL-17A expression by mediating IL-17A mRNA m5C modification in T lymphocytes to induce chronic inflammation." (PMID 37701433, 2023).